TUG1 (taurine up-regulated 1)
Diseases named in the same sentence as TUG1 in open-access papers (continued):
Sharing a sentence is not in itself a finding about the gene and the disease.
cervical cancer (continued). "Our results suggest that TUG1 knockdown activates cytokeratin expression and decreases the expression of vimentin and fibronectin in cervical cancer, partly explaining the metastasis‐related mechanism in this disease." (PMID 28088836, 2017). "Cell wound healing and transwell assays suggested that TUG1 knockdown inhibits the migratory and invasive ability of cervical cancer cells." (PMID 28088836, 2017). "TUG1 expression is upregulated in cervical cancer, where it correlates with larger tumor size, advanced FIGO stage, lower differentiation, and lymph node metastasis." (PMID 28088836, 2017). "Overexpression of lncRNA TUG1 promoted cervical cancer cell proliferation and migration via the progression of epithelial-mesenchymal transition." (PMID 29245996, 2017). "TUG1 was found to be significantly upregulated in cervical cancer tissues and four cervical cancer cell lines by quantitative real‐time polymerase chain reaction (qRT‐PCR)." (PMID 28088836, 2017). "Next, we explored the correlation between TUG1 expression and the clinicopathological characteristics of 40 cervical cancer patients." (PMID 28088836, 2017). "Studies have shown that TUG1, SNHG5, MBNL1-AS1, HOTAIR and other lncRNAs are significantly increased in cervical cancer tissues and cell,associated with FIGO stage, lymph node metastasis, tumor size and differentiation in patients with cervical cancer." (PMID 38948025, 2024). "Up-regulation of lncRNA TUG1 promoted the proliferation and migration of cervical cancer cells." (PMID 34039257, 2021). "LncRNA TUG1 bound with Pum2 and then promoted cervical cancer progression." (PMID 33999859, 2021). "Specifically, TUG1 can reverse the inhibitory effect of mir-138-5p on cervical cancer cells." (PMID 32883200, 2020). "Similarly, Lei and Mou proposed lncRNA TUG1 to be transported via exosomes from cervical cancer cells to HUVEC cells, increasing their angiogenic capacity." (PMID 32992718, 2020). "Likewise, lncRNAs, such as BLACAT1, LINC00675 and TUG1, promoted the cervical cancer progression by activating Wnt/β-catenin signaling pathway." (PMID 31255182, 2019). "Elevated TUG1 expression was shown to correlate with larger tumour size, the advanced stage of the International Federation of Gynecology and Obstetrics, poor differentiation, and lymph node metastasis in patients with cervical cancer." (PMID 30595764, 2018). "Our results demonstrated that TUG1 affects the motility of cervical cancer cells." (PMID 28088836, 2017). "In addition, we clarified that TUG1 promotes migration and invasion of cervical cancer cells, in part by regulating EMT." (PMID 28088836, 2017). "Therefore, the main objective of this study was to investigate the clinical significance and biological functions of TUG1 in cervical cancer." (PMID 28088836, 2017). "However, the relationship between TUG1 expression level and progression of cervical cancer remains poorly documented." (PMID 28088836, 2017). "We achieved this by transiently transfecting cervical cancer cells with siTUG1 to knockdown TUG1." (PMID 28088836, 2017). "Similarly, the colony‐forming assay showed that clonogenic survival decreased significantly when cervical cancer cells were transfected with TUG1 siRNAs (siTUG1 1# and siTUG1 2#), indicating a proliferation‐promoting function of TUG1 in cervical cancer cells." (PMID 28088836, 2017). "Taken together, our findings indicate that TUG1 acts as an oncogene in cervical cancer and may represent a novel therapeutic target." (PMID 28088836, 2017). "Moreover, published data in the GEO database confirmed that TUG1 is significantly upregulated in cervical cancer compared with normal tissues, including the cervix uteri, oral cavity, palate, and tonsils." (PMID 28088836, 2017). "However, TUG1 regulates miR-138-5p to promote cervical cancer progression." (PMID 35475470, 2022). "Therefore, the results indicated that TUG1 functions as an important oncogene in cervical cancer." (PMID 28088836, 2017).
cervical cancer (continued). "In cervical cancer, lncRNA TUG1 promotes the upregulation of PUM2 expression through interaction with PUM2, enhancing the proliferation and migration of cervical cancer cells." (PMID 32997416, 2020). "TUG1 was additionally found to enhance migration and invasion by regulating epithelial–mesenchymal transition (EMT) in cervical cancer." (PMID 28088836, 2017). "Furthermore, the silencing of TUG1 inhibited cell migration and invasion via the inhibition of EMT in cervical cancer cells." (PMID 30595764, 2018). "In addition, we found that the expression of TUG1 in CIN was higher than that in normal cervical uterus tissue, but lower than that in cervical cancer." (PMID 28088836, 2017).
atherosclerosis (23 papers, 2019 to 2025). A disease characterized by the build-up of fatty material and calcium deposition in the arterial wall resulting in partial or complete occlusion of the arterial lumen. "LncRNA TUG1, which is associated with the development of atherosclerosis, reduces the expression of not only ABCA1 but also ABCG1 at the RNA and protein levels, which probably decreases RCT effectiveness and atherosclerosis progression." (PMID 34940525, 2021). "The level of lncRNA taurine upregulated gene 1 (TUG1) is associated with the development of atherosclerosis." (PMID 34940525, 2021). "Gain- and loss-of-function approaches identified that lncRNA TUG1 was closely related to the progression of atherosclerosis." (PMID 33192490, 2020). "The level of some lncRNAs, such as CASC11, H19, TUG1, and MIAT, can be analysed in serum samples as potential diagnostic markers for atherosclerosis." (PMID 39273193, 2024). "TUG1 is extensively linked with several cholesterol efflux genes, including apolipoprotein M (ApoM), ABCA1, and ABCG1, and consequently with atherosclerosis." (PMID 39273193, 2024). "A previous study linked TUG1 with inflammation as TUG1 knockdown decreased IL-6 and TNF in an animal model of atherosclerosis as well as upregulated inflammatory factor expression by sponging miR-133a in ox-LDL-treated macrophages." (PMID 37736902, 2023). "Using VSMCs stimulated with oxidized LDL as a model of atherosclerosis, it was shown that TUG1 silencing increased miR-148b, leading to a decline in IGF-2 which was found to be a target of miR-148b." (PMID 35597813, 2022). "Zhang L, Cheng H, Yue Y, Li S, Zhang D, He R. TUG1 knockdown ameliorates atherosclerosis via up-regulating the expression of miR-133a target gene FGF1." (PMID 35703653, 2022). "The lncRNA TUG1 (taurine up-regulated gene 1) is believed to act in cardiovascular disease by enhancing atherosclerosis in part through an increase in vascular smooth muscle cell (VSMC) proliferation and survival." (PMID 35597813, 2022). "Their study proved that TUG1 expression level was reversely correlated with PTEN expression in patients with atherosclerosis through competing with PTEN for miR-21 binding." (PMID 36250025, 2022). "Previous research, in particular, revealed a direct relationship between TUG1 knockdown and a decline in the inflammatory response in atherosclerosis." (PMID 35982898, 2022). "PMID: 27508018 Chen C, Cheng G, Yang X, Li C, Shi R, Zhao N. Tanshinol suppresses endothelial cells apoptosis in mice with atherosclerosis via lncRNA TUG1 up-regulating the expression of miR-26a." (PMID 35703653, 2022). "The lncRNA TUG1 was reported to promote the proliferation of VSMCs and atherosclerosis through the miRNA-21/PTEN axis." (PMID 34084771, 2021). "A recent observation indicated lncRNA TUG1 regulates ApoM to promote atherosclerosis progression through miR-92a/FXR1 axis." (PMID 34057025, 2021). "Compared with healthy controls, lncRNA TUG1 was upregulated in serum samples of patients with atherosclerosis." (PMID 33192490, 2020). "LncRNAs, including H19, TUG1, MIAT, and CASC11, can be detected in serum and could serve as potential diagnostic markers for atherosclerosis." (PMID 40941416, 2025). "Moreover, the mentioned positive correlation between TUG1 and cholesterol, TAG, LDL, and carotid IMT confirmed the direct relation of this biomarker to atherosclerosis which is one of the most direct risk factors of AIS." (PMID 36250025, 2022). "Notably, GATA6-AS1 was evidenced as an upstream inhibitor of taurine upregulated gene 1 (TUG1), which is known to play a crucial role in promoting atherosclerosis." (PMID 35053285, 2022). "Also, in atherosclerosis, the elevated expression level of TUG1 increased endothelial cell apoptosis through miR-26a sponging." (PMID 35237654, 2021). "TUG1 was up-regulated and shown to promote cell apoptosis in brain ischemia and atherosclerosis." (PMID 31551710, 2019).
atherosclerosis (continued). "A previous study showed TUG1 knockdown could ameliorate atherosclerosis via inducing FGF1 expression." (PMID 30873207, 2019). "So, they considered that TUG1 could be a potential target for treating atherosclerosis." (PMID 36250025, 2022). "Similarly, many recent studies have discussed the role of TUG1 in atherosclerosis." (PMID 35237654, 2021). "Deregulation of lncRNAs, including H19, TUG1, GAS5, RAPIA, MIAT, CASC11, NEXN-AS1, and lnc00113, has been observed in individuals with atherosclerosis." (PMID 40941416, 2025). "The deregulation of many lncRNAs, including RAPIA, H19, CASC11, GAS5, TUG1, MIAT, lnc00113, and NEXN-AS1, has been observed in patients with atherosclerosis." (PMID 39273193, 2024). "Few recent studies indicated the signaling pathway of TUG1 by increasing TNF via the activation of the NF-KB pathway by regulating miR-26a/HMGB1 and development of atherosclerosis through modulating miR-21/phosphatase." (PMID 37736902, 2023). "Interestingly, we observed several well-known lncRNAs, such as TUG1, PCA3, and HOTAIR, which were also involved in regulating atherosclerosis progression." (PMID 30873207, 2019).
esophageal squamous cell carcinoma (20 papers, 2015 to 2022). Esophageal squamous cell carcinoma (ESCC) is a type of esophageal carcinoma (EC) that can affect any part of the esophagus, but is usually located in the upper or middle third. "Up-regulation of lncRNA TUG1 promoted the proliferation and migration of esophageal squamous cell carcinoma." (PMID 34039257, 2021). "The lncRNA taurine upregulated gene 1 (TUG1) (NCBI GeneID: 55000) was also demonstrated to suppress PDCD4 by recruiting EZH2 in esophageal squamous cell carcinoma (ESCC) through epigenetic modification." (PMID 31620370, 2019). "In addition, a previous document revealed that elevated TUG1 expression was closely correlated with chemotherapy resistance of esophageal squamous cell carcinoma." (PMID 28376901, 2017). "In prostate and esophageal squamous cell carcinoma (ESCC), TUG1 directly binds NRF2, thus upregulating its expression at protein level together with its downstream members (HO-1 and NQO1)." (PMID 33287295, 2020). "Inhibition of TUG1 can inhibit the proliferation and invasion of cells by up-regulating miR-498 and down-regulating CDC42 in esophageal squamous cell carcinoma cells." (PMID 32391554, 2020). "LncRNA TUG1 was frequently upregulated and characterized as an oncogene involved in the development and progression of a variety of tumors (e.g., osteosarcoma, esophageal squamous cell carcinoma (ESCC), urothelial carcinoma of the bladder, glioblastoma, colorectal cancer)." (PMID 28404901, 2017). "After that, TUG1 was found to have an important role in other cancers such as LC, HCC, BC, OC, GC, CRC, esophageal squamous cell carcinoma (ESCC), osteosarcoma, glioma, and bladder cancer." (PMID 31480503, 2019).
prostate carcinoma (17 papers, 2016 to 2025). A carcinoma that arises from epithelial cells of the prostate gland. "More specifically, a number of studies have documented a tumor-promotive role of TUG1 in several malignancies such as cervical cancer, prostate cancer, and especially CRC." (PMID 35508523, 2022). "For instance, a study reported that TUG1 was overexpressed in prostate cancer and promoted tumor cell migration, invasion, and proliferation by negatively modulating miR-26a expression." (PMID 36157241, 2022). "Knockout of lncRNA TUG1 enhanced the radiosensitivity of prostate cancer through the lncRNA TUG1/miR-139-5p/structural maintenance of chromosomes protein 1A (SMC1A) axis." (PMID 34039257, 2021). "Among the remaining 8 lncRNAs, three lncRNAs, TUG1, IGF2-AS and CDKN2B-AS1, are found in the database LncRNADisease, and they are all associated with prostate cancer." (PMID 33980147, 2021). "LncRNA TUG1 increases cisplatin resistance in prostate cancer and esophageal cancer by the Nrf2 signal axis." (PMID 34466284, 2021). "Down-regulation of lncRNA TUG1 inhibited the development and progression of prostate cancer by regulating the microRNA496/wnt/β-catenin pathway." (PMID 34039257, 2021). "Finally, high expression of TUG1 correlates with progression of the disease and less favorable survival profiles in prostate cancer patients." (PMID 36831650, 2023). "In prostate cancer, lncRNA TUG1 enhanced radioresistance through miR-139-5p/SMC1A axis." (PMID 35600868, 2022). "lncRNA TUG1 accelerated the progression of prostate cancer by regulating the MIR-128-3p/YES1 axis." (PMID 34039257, 2021). "lncRNA TUG1, as the ceRNA of miR-26a, promoted the progression of prostate cancer." (PMID 34039257, 2021). "TUG1 may serves as a potential target for treatment of prostate cancer patients." (PMID 37025585, 2023). "Notably, a previous study highlighted that TUG1 could bind to miR-26a, and further negatively regulated its expression to accelerate the progression of prostate cancer." (PMID 35508523, 2022). "As an example, in prostate cancer, cytoplasmic lncRNAs, like CTB-89H12.4 and Taurine Upregulated Gene 1 (TUG1), act as miRNA sponges to down-regulate PTEN, which affects the PI3K/Akt pathway." (PMID 40725427, 2025). "A number of well-known oncogenic lncRNAs in other cancers such as DANCR, MALAT1, CCAT1, PVT1, TUG1 and NEAT1 have also been shown to act as oncogenes in prostate cancer." (PMID 37025585, 2023). "We confirm the tumour-suppressive function of two lncRNAs (TUG1 and CTB-89H12.4) and their regulation of PTEN expression in prostate cancer." (PMID 26975529, 2016). "Previous studies have demonstrated that taurine-upregulated gene 1 (TUG1) was aberrantly expressed and involved in multiple types of cancer; however, the expression profile and potential role of TUG1 in prostate cancer (PCa) remains unclear." (PMID 29967294, 2018).
diabetes (16 papers, 2020 to 2025). "The aim of this study was to assess the diagnostic roles of lncRNA H19 and TUG1 for IBS associated with diabetes and to evaluate their association with clinical and laboratory findings." (PMID 36428545, 2022). "Accordingly, lncRNA Tug1 may be an attractive target for the development of new therapeutic strategies to treat numerous chronic diseases linked to metabolic impairments in skeletal muscle such as type 2 diabetes mellitus, obesity and cardiovascular diseases." (PMID 35850762, 2022). "LncRNA TUG1 (taurine upregulated gene 1) has emerged as a potential epigenetic modulator in diabetes and diabetes-related diseases." (PMID 39273193, 2024). "During insulin secretion and synthesis, the transcription factor Glut2, which controls transport, and the transcription factors Pdx1, MafA and NeuroD, which control synthesis, are regulated by lncRNA TUG1, and interference with lncRNA TUG1 leads to diabetes." (PMID 36225311, 2022). "Based on these findings, they proposed that lncRNA TUG1 promoted the browning of white adipose tissue by regulating miR-204/SIRT1 axis to ameliorate diabetes." (PMID 36555704, 2022). "The current results demonstrated that using TUG1 to diagnose diabetes with stroke yielded an AUC of 0.954 (95% CI = 0.915–0.994, p < 0.001), with a sensitivity of 87.9% and a specificity of 98.5%." (PMID 35237654, 2021). "Previous studies reported that the expression of TUG1 was decreased in rats with diabetes and in mesangial cells induced with high-level glucose through inhibition of the PI3K/AKT pathway." (PMID 35237654, 2021). "Tug1, an important player in the metabolic response of podocytes in diabetes mellitus, is indeed also expressed in podocytes in our data and—in line with current knowledge—conserved in humans." (PMID 33804736, 2021). "Additionally, TUG1 silencing ameliorates diabetes mellitus-induced retinal vascular impairment in vivo." (PMID 35599572, 2022). "lncRNA TUG1 was shown to influence mitochondrial activity in podocytes in diabetes conditions." (PMID 35599572, 2022). "The current study, for the first time, revealed that serum TUG1, LINC00657, miR-9, and miR-106a may serve as novel potential indicators of stroke associated with diabetes and correlated significantly with NIHSS." (PMID 35237654, 2021). "It was observed that TUG1 expression is decreased in a non-obese diabetic animal model and its downregulation is associated with diabetes." (PMID 32368256, 2020). "Besides, lncRNA Tug1 overexpression in PCs improved diabetes-induced chronic kidney disease." (PMID 32550905, 2020). "In conclusion, our study revealed the upregulation of the lncRNAs MALAT1,MEG3, and TUG1 in patients within the first five yearsof diagnosis of T1DM compared to controls and long-term diabetes group." (PMID 41123190, 2025). "Transgenic mice that overexpressed TUG1 in podocytes were protected from diabetes-induced CKD, while glomerular TUG1 levels were reduced in both mice and renal biopsies from diabetic patients." (PMID 37190024, 2023). "Multivariate regression analysis (considering NIHSS as the dependent variable) confirmed that TUG1 and LINC00657 were independent predictors for diabetes with stroke (p = 0.04 and p = 0.01, respectively)." (PMID 35237654, 2021). "Moreover, transgenic mice that overexpressed Tug1 specifically in podocytes were protected from diabetes-induced CKD, suggesting that this lncRNA may be a possible therapeutic target to treat kidney disease and/or diabetes." (PMID 34199920, 2021).